EGFR (epidermal growth factor receptor)
Diseases named in the same sentence as EGFR in open-access papers (continued):
Sharing a sentence is not in itself a finding about the gene and the disease.
tumor (continued). "Many GBM tumor cells express a mutated form of EGFR, EGFRvIII." (PMID 38920629, 2024). "The tumor characteristics and EGFR mutation rates were compared between different age groups." (PMID 39722087, 2024). "EGFR‐TKI therapy has been associated with changes in the tumor immune microenvironment of EGFR‐mutated NSCLC, which may provide clues for further optimization of PD‐1 inhibitor therapy." (PMID 39406371, 2024). "The cobas EGFR Mutation Test (v1) was FDA-approved on May 14, 2013 for the qualitative detection of exon 19 deletions and exon 21 (p.(Leu858Arg)) substitution mutations of the EGFR gene in DNA derived from FFPE human NSCLC tumor tissue." (PMID 39063150, 2024). "The unavailability of tumor tissue, uncommon driver mutations, rare EGFR mutation subtypes, and the limitation of conventional genetic testing are possible reasons that may explain the missing detection of driver mutation(s) at diagnosis." (PMID 39000058, 2024). "EMT, the process by which epithelial cells acquire mesenchymal features, is associated in cancer with tumor invasion, initiation, metastasis, and resistance to therapy, notably with EGFR and ALK inhibitors in EGFR-mutation-positive and ALK-fusion-positive NSCLC models." (PMID 39301544, 2024). "Liquid biopsy is one of the most transformative methods, enabling the detection and monitoring of EGFR mutations through circulating tumor DNA (ctDNA) in blood samples, with numerous studies highlighting its clinical utility and concordance with tissue-based genotyping." (PMID 39834943, 2024). "Secondary endpoints include health-related quality of life (HRQoL), MPR in patients with or without detectable EGFRm at screening in ctDNA, and the concordance of EGFR mutation status between baseline tumor DNA and ctDNA samples, as well as between local and central tumor test results." (PMID 39624538, 2024). "Compared with common EGFR-mutated NSCLC, PD-L1 expression in tumor tissues with rare EGFR mutations is relatively high, implying that it may benefit from immunotherapy." (PMID 38774882, 2024). "However, few studies reported the association between the PTS of tumor and the clinical benefits of third-line anti-EGFR mAbs treatment in the Asian patient population." (PMID 38217945, 2024). "Furthermore, the dysregulation of the EGFR signaling network is associated with tumor formation and invasion." (PMID 38933923, 2024). "Notably, radiological responses align with liquid biopsy observations: in both instances, follow-up liquid biopsies indicate the clearance of EGFR-mutated circulating tumor DNA (ctDNA)." (PMID 38529368, 2024). "The EGFR mutation could also be detected in the benign epithelium surrounding the tumor, demonstrating that it is an early event in carcinogenesis." (PMID 38953007, 2024). "Importantly, ABT-806 exhibits nearly 10-fold greater affinity for overexpressed, tumor-associated EGFR versus WT-EGFR." (PMID 39065587, 2024). "Overexpression of EGFR is associated with increased tumor growth and invasiveness." (PMID 39518088, 2024). "Comparison of EGFR mutations between peripheral blood ctDNA and tumor tissues." (PMID 39634906, 2024). "Since PDOs are also reliable platforms for testing drug efficacy and predicting patient drug response, we evaluated the expression of HER-2 and EGFR as cell surface-associated tumour biomarkers to identify the most suitable candidate therapeutic targets in this specific case." (PMID 38926706, 2024). "Furthermore, high mutation rate of EGFR in East Asian populations together with the inert tumor immune microenvironment in lesions presenting as pGGN collectively implied a heterogeneous and limited response to immunotherapy in patients with MPLC." (PMID 38668781, 2024).
tumor (continued). "EGFR-19 Del mutations may suppress anti-tumor immunity by inactivating DCs via EVs, weakening the tumor microenvironment." (PMID 39772073, 2024). "MPE was a reliable surrogate for tumor tissue in identifying EGFR mutations." (PMID 39596989, 2024). "Moreover, genomic variants that were found to be predictive of anti-EGFR resistance in other tumour types are infrequent in TNBC patients, suggesting that non-genomic mechanisms of resistance must be at play in TNBCs." (PMID 38605363, 2024). "Univariable and multivariable analysis were used to explore the factors affecting DFS and OS for EGFR-mutated stage IA patients, adjusting for age, sex, smoking history, tumor laterality, resection type, T stage, TPM group, predominant subtype, and EGFR mutation status." (PMID 39232762, 2024). "Several oncogenic signaling pathways, such as Akt/mTOR, JAK/STAT3, and EGFR/MAPK, or the loss or silencing of PTEN, ALK, and EGFR, are involved in the regulation of PD-L1 transcription, potentially leading to the upregulation of PD-L1 expression in tumor cells." (PMID 38762484, 2024). "This implies that NSCLC patients with EGFR-sensitive mutations and high PD-L1 expression may harbor a higher burden of genetic mutations, potentially influencing tumor-related pathways." (PMID 38238740, 2024). "Notably, the migratory tumor subtype was closely linked to genomic alterations of EGFR, related to the tumor-promoting behavior of IL6-positive inflammatory tumor-associated fibroblast, and contributing to poor prognosis." (PMID 38892065, 2024). "Similarly, overexpression studies have shown how certain mutations, such as those in the EGFR gene, can promote aggressive tumor behavior." (PMID 39457373, 2024). "Finally, EGFR is one of the most well-known tyrosine kinase receptor domain-containing proteins and is commonly mutated in tumor, with uncontrolled cell growth, proliferation, and migration documented in approximately 33% of NSCLCs." (PMID 38499532, 2024). "Additionally, the expression of TGF-β1 (P = 0.0013) and TGF-β3 (P = 0.0028) was significantly higher in EGFR20ins-mutated tumors than in EGFR WT tumor tissues." (PMID 39004699, 2024). "Additionally, an end-to-end approach that includes automatic tumor recognition, localization, and EGFR mutation prediction can be developed." (PMID 39619439, 2024). "The EGFR mutation rates were varied among different tumor characteristics and age at diagnosis." (PMID 39722087, 2024). "Finally, RNAscope in situ hybridisation (ISH) analysis further confirmed the presence of distinct transcripts (Socs2, Srsf2, Birc2) in endothelial cells associated with MES-GSC-driven and EGFR expressing tumours." (PMID 38570528, 2024). "Antibody and small-molecule inhibitors of EGFR were some of the first approved signaling pathway-targeted inhibitors, and are used extensively in tumors bearing EGFR mutations or with EGFR overexpressed, as well as in other contexts in which EGFR signaling contributes to tumor growth and survival." (PMID 38639476, 2024). "The relation between tumor biomarkers and EGFR mutation has been elucidated in previous studies." (PMID 38980474, 2024). "Recent research has explored the genetic alterations in these tumors, revealing dissimilarities in the frequently mutated genes, the role of EGFR in carcinogenesis, the presence of transcription factors, and the immunogenicity of the tumor and its microenvironment." (PMID 38539512, 2024). "In addition, the mean of tumor maximum diameter in the EGFR mutation group was larger than the control group." (PMID 37436674, 2024). "Recently, the phase III ADAURA clinical trial has certificated a dramatically better clinical benefits in disease-free survival (DFS) of patients in stage IB-IIIA LUAD harboring EGFR mutations treated by osimertinib after completely resection of tumor compared with placebo group." (PMID 38528507, 2024).
tumor (continued). "Furthermore, the tumor suppressive activity of DB-1310 is independent to the EGFR mutation and sensitivity to EGFR-TKi." (PMID 38632563, 2024). "Moreover, with the help of the DL model, the sub areas within the tumour that are strongly related to EGFR mutation status can be identified and further subjected to biopsy if required." (PMID 38539465, 2024). "Two of the studies included in the analysis have demonstrated that silencing tumor-derived exosomal circRNA_102481 can enhance apoptosis in EGFR-TKIs resistant NSCLC, while the loss of circRNA vacuolar membrane protein 1 similarly promotes apoptosis of cisplatin-resistant NSCLC." (PMID 39872524, 2024). "In all three putative mosaic cases with L858R EGFR-mutant tumors, the L858R mutation was detectable in multiple, anatomically distinct, normal lung samples, albeit at much lower allele fractions than in the tumor samples." (PMID 39406916, 2024). "Aberrant EGFR amplification or mutation may influence the activation of signaling networks that promotes irregular cell growth and survival, ultimately driving tumor progression." (PMID 38418476, 2024). "Finally, if repeated genetic tests on tumor tissue or peripheral blood ctDNA show a consistent mutation abundance of 50% for EGFR T790M, it is likely indicative of a germline mutation, and testing for EGFR germline mutations is recommended." (PMID 39160638, 2024). "In liquid biopsy samples, circulating tumor DNA (ctDNA) derived from tumor cells may contain eccDNA fragments carrying EGFR mutations or amplifications." (PMID 39202666, 2024). "Interestingly, one novel compound was found to suppress tumor proliferation in EGFR-mutated NSCLC through activating JNK/p38 MAPK pathways, indicating the variable functionality of these pathways." (PMID 39062063, 2024). "Furthermore, as we deepen our understanding of EGFR mutations and their intricate roles in tumor biology, we can expect the development of increasingly tailored therapeutic approaches that enhance treatment efficacy and improvement of patient care." (PMID 39518531, 2024). "It is important to note here that, because Akt plays a central role in metabolism and cell proliferation, the PI3K-Akt pathway drives tumorigenesis and/or tumor growth in some cancers via mutations in Akt or upstream proteins (e.g., in EGFR or PI3K) that result in aberrant activation of the pathway." (PMID 38891035, 2024). "The patient’s tumor responded well to erlotinib but developed resistance after the acquisition of the T790M mutation, the most common type of resistance to first- or second-generation EGFR-TKIs." (PMID 38398169, 2024). "Thus, the detection of EGFR mutations as circulating tumor DNA (ctDNA) in body fluids, such as blood plasma, can be applied in clinical decisions related to targeted EGFR therapies." (PMID 39189452, 2024). "This limitation may be linked to the complexity of the EGFR signaling pathway, variations in the tumor microenvironment, and resistance to immunotherapy." (PMID 39640262, 2024). "Therefore, it is very important to determine the EGFR gene mutation status of patients through tumor tissue for making personalized treatment plans for NSCLC patients." (PMID 38396128, 2024). "In this context, evidence has characterized that EGFR‐mutated tumors have a lower tumor mutation burden (TMB), but the association with PD‐L1 expression remains unclear." (PMID 38456253, 2024). "In addition, ALK-positive adenocarcinomas tend to present a more rapid metastases to lymph nodes or distant sites compared with EGFR mutation or with wild type, indicating that the tumor is more aggressive." (PMID 39497711, 2024). "We hypothesized that, by utilizing this feature, we could obtain the probability of EGFR mutation in the entire tumor region and calculate the EGFR prevalence in WSI." (PMID 39358807, 2024).
tumor (continued). "Moreover, EGF secreted by TAMs, causes EGFR activation in tumor cells, which upregulated the VEGF/VEGFR signaling pathway in the surrounding, thus stimulating the proliferation and migration of cancer cells." (PMID 39003350, 2024). "Vitro studies have shown that repetitive mutation in EGFR exons 18-25 kinase domain lead to constitutive activation of the EGFR kinase, resulting in over-activation of downstream signaling pathways, promoting cell proliferation and tumor development." (PMID 38974236, 2024). "During our analysis, we observed significant differences in clinical characteristics such as gender, smoking history, type of nodules, tumor long axis, and tumor short axis between patients with EGFR mutations and those with wild-type EGFR (with p < 0.05 in both the training and test sets)." (PMID 38438844, 2024). "We evaluated factors related to postoperative tumor recurrence among cases with EGFR mutations." (PMID 39281386, 2024). "Furthermore, EGFR inhibition in NSCLC cells with EGFR mutations promotes a tumor microenvironment linked to immune evasion." (PMID 38279998, 2024). "These mutations enhance the responsiveness of tumor cells to EGFR inhibitors." (PMID 38611728, 2024). "Tumours with EGFR, ALK, BRAF mutations may be resistant to PD-1/PD-L1 immunotherapy, and are more suitable for targeted therapy or combination therapy." (PMID 39530091, 2024). "In addition to its potential involvement in ERCC1-deficient NSCLC, PARPI can inhibit tumor growth in NSCLC with epidermal growth factor receptor (EGFR) mutations." (PMID 38566036, 2024). "However, a significant association of EGFR positivity with tumor size and lymph node status was reported in other studies." (PMID 39405290, 2024). "Our analysis of poly(G) repeats in such tumors suggests that EGFR mutations may occur before cells have undergone half of the divisions on their way to tumor initiation." (PMID 39406916, 2024). "Abnormalities of EGFR are widely associated with tumorigenesis and tumor progression." (PMID 38914986, 2024). "After verification between the total cohort and the EGFR mutation testing cohort, older age was associated with an increased likelihood of having more patients with a tumor diameter >2 cm (p < 0.001), mixed GGOs with a CTR >0.5 (p < 0.001), IAC (p < 0.001), and pathologic stage IA2–IB (p < 0.001)." (PMID 39722087, 2024). "We also analyzed genetic mutations using tumor specimens from the primary lung lesion, metastatic choroidal lesion and blood; then we will discuss the mechanisms of choroidal resistance to EGFR-TKI treatment and the mechanism of oligo-resistance in the choroid." (PMID 38962043, 2024). "Differences in outcomes with anti-EGFR treatment in mCRC may be attributed to tumor genomic and molecular profiles associated with primary resistance to EGFR inhibition, such as the BRAF V600E mutation and high microsatellite instability (MSI-H), among others." (PMID 38347302, 2024). "Interestingly, after stratification by different characteristics, the EGFR mutation rate remained significantly different between different age groups in the tumor diameter ≤2 cm (p < 0.001), pure GGOs (p = 0.001), and IAC (p = 0.039) cohorts." (PMID 39722087, 2024). "In response to the cell-cycle inhibition, tumor cells may upregulate EGFR to bypass the growth inhibition caused by stress." (PMID 39668430, 2024). "A comparison of the PDC drug sensitivity and clinical tumor response showed that the PDC AUC values for EGFR- or ALK-TKIs were significantly associated with the clinical tumor response (median standardized AUC values: −0.78 in PR, −0.29 in SD, and 0.30 in PD; p < 0.001)." (PMID 38398169, 2024). "The model with tumor CT features showed that tumor located in ILA (OR = 0.156, 95% CI: 0.046–0.529; p = 0.003) and tumor diameter (OR = 0.592, 95% CI: 0.415–0.846; p = 0.004) were independent predictors of EGFR mutation; the corresponding AUC value was 0.838 (95% CI: 0.754–0.922, p < 0.001)." (PMID 38783331, 2024).
tumor (continued). "An explanation for ICI resistance of the EGFR mutated tumors could be the upregulation of expression of the checkpoint molecules and their receptors that favors tumor immune escape." (PMID 39148899, 2024). "Furthermore, REGN5093-M114 effectively reduced tumor growth in EGFR-mutant NSCLC cases with PTEN loss or c-MET-Y1230C mutation, even in cases of prior progression on osimertinib and savolitinib treatment." (PMID 39664377, 2024). "For example, while one tumor region may show sensitivity to a specific therapy targeting EGFR amplification, another region might harbor mutations like TERT promoter alterations that drive treatment resistance." (PMID 39767571, 2024). "Inhibition of the cell cycle, induction of apoptosis, activation of the immune system, and interference with key signaling pathways such as EGFR, Nrf2/p62, and miR-7-5p/Akt/Wnt-β-catenin were some of the proposed underlying anti-tumor mechanisms mediated by PA-MSHA." (PMID 38339275, 2024). "Therefore, inhibiting EGFR expression in EGFR-mutated tumors has clinical benefits that can help combat drug resistance and reduce tumor growth." (PMID 38831321, 2024). "The mechanisms underlying osimertinib resistance, which may be associated with tumor evolution, clonal heterogeneity, and selection pressure, can be categorized into two types: EGFR-dependent (on-target) and EGFR-independent (off-target) mechanisms." (PMID 39324002, 2024). "Similarly, we compared the clusters of murine (stromal) cells within both EGFR-proficient and -deficient tumours, which were biologically annotated based on the relative abundance of top-ranking marker genes." (PMID 38570528, 2024). "Furthermore, signals associated with tumor metastasis, such as EGFR tyrosine inhibitor resistance and focal adhesion, were strongly correlated with these genes." (PMID 38566155, 2024). "Hence, to clearly investigate the associations between tumor characteristics, age, and EGFR mutation rates in patients with GGOs, we performed an analysis of GGOs in a large-scale cohort from two cancer centers." (PMID 39722087, 2024). "Additionally, the risk of EGFR mutations increased with larger tumor diameter, tumor imaging presentation of mixed ground glass opacity (mGGO), and tumor pathological findings of minimally invasive adenocarcinoma (MIA) or invasive adenocarcinoma (IAC)." (PMID 38126071, 2023). "However, mutations of the EGFR gene leading to independence from the ligand binding result in constant stimulation of uncontrolled cell proliferation and, as a result, tumor growth." (PMID 36817482, 2023). "On the other hand, there was also synergy between antiangiogenic agents and immune checkpoint inhibitors, and antiangiogenic agents showed immunomodulatory effects, could improve the tumor microenvironment for immunosuppression in patients with EGFR mutations." (PMID 37869096, 2023). "According to the previous publication, EGFR amplification usually correlate with EGFR overexpression and may associate with a more aggressive tumor stage." (PMID 36325957, 2023). "In the EGFR mutation-positive group, higher tumor-frequency regions consisted of three clusters located in the left cerebellum, part of cuneus in the left occipital lobe and precuneus in the left parietal lobe and the precentral gyrus of the right frontal lobe." (PMID 37508989, 2023). "In mice bearing patient-derived LU0858 tumors (harboring the EGFR-activating L858R mutation and METamp), gefitinib and afatinib had no inhibitory effect on tumor growth whereas tepotinib alone delayed tumor growth significantly, and tepotinib combined with EGFR-TKIs caused complete tumor regression." (PMID 36999986, 2023).